STAT3 (signal transducer and activator of transcription 3)
Diseases named in the same sentence as STAT3 in open-access papers (continued):
Sharing a sentence is not in itself a finding about the gene and the disease.
cancer (continued). "CAF has been demonstrated to confer 5-fluorouracil (5-FU) resistance to GC cells by expressing neuropilin 2 (NRP2), eventually activating the Hippo pathway and alternatively activating JAK/STAT3 in cancer cells via secreting cytokines." (PMID 37784082, 2023). "Research has shown that regulatory T cells (Tregs) promote cancer stemness in gliomas through the TGF-β/NF-κB/IL-6/STAT3 signaling axis." (PMID 38164743, 2023). "Many human cancers, including HCC, have constitutively activated signal transducer and activator of transcription 3 (STAT3) pathway, which plays an essential role in cell proliferation and multiplication in such cancers." (PMID 35285010, 2023). "Our study emphasizes the importance of distinguishing between STAT3α and STAT3β proteins and their active forms when discussing STAT3-related cancer diagnosis and therapy." (PMID 37097001, 2023). "Consistently, it was noted that the gain of STK24 increased expression levels of STAT3 in A549 and H226 cancer cells." (PMID 36720310, 2023). "The Zhe Ji groups have demonstrated that the inflammatory regulation network mediated by NFκB, STAT3, and AP-1 factors is essential in many cancers." (PMID 37821959, 2023). "STAT3 also acts as an immunotherapy target in many cancers by inhibiting profound immune-stimulating factors, including chemokines (CCL5, CXCL10) and interferons (IFNs)." (PMID 37173892, 2023). "Nevertheless, it also plays a role in pathological conditions such as cancer by activating the STAT3, MAPK, and PKB/Akt pathways, and NF-kB." (PMID 37892997, 2023). "Gastric CSCs facilitate the development of cancer stem cells through STAT3 signaling pathway while protecting CSCs from being recognized by T cells." (PMID 36810098, 2023). "Specifically, the authors identified that HSP90 cooperated with STAT3 to regulate TWIST1 levels in cell lines from multiple cancer types, including OvCa." (PMID 37173951, 2023). "Furano[2,3-b]naphtho-4,9-dione 12b, isolated from Tabebuia avellanedae, shows a preference for inhibition of cancer cell growth over normal cells, with STAT3 inhibitory mechanisms proposed, while other FNQ natural products inhibit IDO1 (see Section 3.1.3)." (PMID 37446864, 2023). "In light of this challenge, our investigation into the interaction of PRMT6 with JAK2 to activate the STAT3 pathway led us to consider PRMT6 inhibitors as a potentially effective approach for cancer treatment." (PMID 37813837, 2023). "The IL-6/STAT3 signaling pathway upregulates factors involved in cancer cell proliferation (MYC, cyclin D1), angiogenesis (VEGFA, PDGF), and apoptosis (Bcl-XL)." (PMID 36720310, 2023). "Given the upregulation of STAT3 in several cancers, the upregulation of thioredoxin 1 in its reduced form in neoplastic tissues is undesirable, as it will prompt downstream signaling mediated by STAT3." (PMID 37107311, 2023). "Such abnormal activation of STAT3 often leads to malignant cellular transformation and, therefore, it is considered as a potential target molecule for cancer therapy." (PMID 37190167, 2023). "It has been previously reported that HSP90, together with IL6/STAT3 signaling, is essential for the progression of various diseases, infections, and cancers." (PMID 37099596, 2023). "4-hydroxytamoxifen (OHT, an active metabolite of tamoxifen), alpelisib, the p21 (CDKN1A) inhibitor UC2288, and the STAT3 inhibitor C188-9 showed a wide TW, and hence, more selectivity for cancer cells and less toxicity as monotherapies." (PMID 36869202, 2023). "Due to the positive roles in cancer development, STAT3 has become an appealing drug target for anti-cancer therapy." (PMID 36656267, 2023). "In human cancers, STAT3 is generally hyperactivated and drives tumorigenesis, thus acting as an oncoprotein 15-17." (PMID 37564211, 2023). "A key role for IL-6/JAK/STAT3 in the regulation of the growth, survival, invasiveness, metastasis, and progression of many cancers was shown." (PMID 37753372, 2023).
cancer (continued). "STAT3 is central to anti-cancer, and participates in cancer progression, differentiation and metastasis." (PMID 36982538, 2023). "Phosphorylation of STAT3 on tyrosine 705 (Y705) is considered a marker for STAT3 activation and is well documented across multiple cancer types." (PMID 37097001, 2023). "According to the literature, the JAK/STAT3 pathway is one of the vital signaling pathways responsible for cancer cell proliferation and metastasis." (PMID 37894738, 2023). "In many solid tumors, STAT3 is activated in groups, providing proliferation signals to cancer cells." (PMID 37875983, 2023). "The major gene targets of four core herbs, MMP9, BCL2, STAT1, and STAT3, each as a subset of pathways in cancer, were confirmed to be involved in the MAPK pathway, the mTOR pathway, and cytokine–cytokine receptor interaction." (PMID 37631075, 2023). "This mutual regulation of XIST and STAT3 further supports a role of XIST in promoting cancer stemness." (PMID 36922677, 2023). "Taken together, we designed and synthesized a novel small molecule JAKs inhibitor targeting the JAK/STAT3 signaling pathway, which has predicted therapeutic potential for JAK/STAT3 overactivated cancer treatment." (PMID 37103357, 2023). "In summary, alterations in STAT3 are involved in carcinogenesis and cancer progression, especially in hematologic malignancies." (PMID 36977736, 2023). "As a member of the cytokine receptor family, STAT3 plays an important role in the proliferation and metastasis of various cancers." (PMID 37298609, 2023). "According to reports, the activation of STAT3 signaling is the main intrinsic pathway for the occurrence and development of various cancers." (PMID 37875983, 2023). "designed a new nanodrug delivery system to improve the solubility of poorly soluble drugs and the inhibition of STAT-3, thereby enhancing the anti-cancer effect." (PMID 37143168, 2023). "Taken together, our data identify cytosolic acidification and STAT3 inhibition as novel anticancer mechanisms of clinically relevant CADs and provide a novel drug combination strategy for cancer therapy." (PMID 36807142, 2023). "Since STAT3 plays an important role in cancer survival and apoptosis, and our finding demonstrated that STAT3 was the most relevant core target, the effect of AB on STAT3 activity was then investigated." (PMID 36707691, 2023). "In healthy cells, the STAT3 remains inactive, while it activates when the cell is experiencing unfavorable circumstances including cancer and other disease conditions." (PMID 37978263, 2023). "STAT3, a highly conserved transcription factor, has also been reported to be overexpressed in various types of cancer and promotes carcinogenesis through modulating cell proliferation, apoptosis, EMT, metastasis and drug resistance." (PMID 36334221, 2023). "The JAK2/STAT3 signaling pathway is a crucial target among the three ATLs pathways for cancer therapy." (PMID 37241729, 2023). "STAT3 is a direct transcription factor that plays important roles in inflammation, cancer, angiogenesis, and immunosuppression." (PMID 37511525, 2023). "In summary, previous studies found that some Eups can significantly inhibit cancer cell proliferation by inhibiting STAT3 and Akt signaling pathways, inducing apoptosis, cell cycle arrest, and DNA damage response." (PMID 37049904, 2023). "From 2017 to 2022, the predominant focus of research on CAFs pertained to cancer treatment, with particular emphasis on STAT3, multidrug resistance, ionizing radiation (IR), and gold nanoparticles (GNPs) emerging as prominent areas of investigation." (PMID 38173726, 2023). "Targeting the STAT3 protein through high-affinity ligands to reduce its levels or activity in cancer has noteworthy therapeutic potential." (PMID 37298475, 2023). "Recent investigations have demonstrated that the anti-cancer activity of the three atractylenolides can be attributed to their influence on the JAK2/STAT3 signaling pathway." (PMID 37241729, 2023).
cancer (continued). "The signal transducer and activator of transcription 3 (STAT3) signaling pathway's ability to increase cancer cell proliferation, invasion, and the development of chemical resistance in GC is currently well recognized." (PMID 37415625, 2023). "Since the discovery of STAT3, the role of IL-6/JAK/STAT3 signaling has been widely studied in various cancers." (PMID 37237509, 2023). "STAT3 is key target in cancer immunotherapy, which is important in enhancing anti-cancer immune responses by rescuing the suppressed immunologic microenvironment in tumors." (PMID 38136311, 2023). "In this review, we evaluate the scientific and medical literature that elucidate STAT3-mediated mechanisms of resistance to cancer therapeutics." (PMID 36902166, 2023). "Overall, we found that STAT3 significantly predicted cancer prognosis, drug resistance, and immunotherapy, providing a rationale for further experimental studies." (PMID 36977736, 2023). "In epithelial ovarian cancer cells, the activation of the CSF2/p-STAT3 pathway leads to the enhancement of stem cell-like properties in cancer cells." (PMID 38003292, 2023). "STAT3 is a well-known regulator of cytokine signalling and a target for inducing apoptosis in other cancer types." (PMID 37173994, 2023). "Under a cancer context, it is known that STAT3 signaling regulates the CD5 expression, but in the TB context, this signaling has not been clarified; further studies are necessary to identify the molecules involved to favor the expansion of CD5+ B cells in LTB." (PMID 37375508, 2023). "Previous studies have shown that CAFs promote carcinoma progression by inducing EMT via the IL-6/JAK2/STAT3 pathway or paracrine TGF-β." (PMID 37254126, 2023). "STAT-3 is found to be constitutively active in different carcinomas and inhibition of STAT-3 activation correlates with suppression of malignant cells both in vivoand in vitro." (PMID 37720284, 2023). "Sorafenib is a multikinase inhibitor that promotes apoptosis by targeting STAT3 signaling in a variety of carcinomas, including pancreatic cancer and glioblastoma." (PMID 38203502, 2023). "We uncovered an unpredicted immunosuppressive function of IL-6/STAT3 pathway in cancer cells affecting the expression of potent neoantigens under the control of NMD." (PMID 36443756, 2022). "The hyperactivation of STAT3 signaling has been observed in most human cancer cases, and abnormal levels of IL-6, stimulating STAT3, are commonly found in patients suffering from chronic disease, such as IBD or RA." (PMID 35631173, 2022). "Regarding cancer cell invasion, the activation of STAT3 by oncogenic proteins is one of the most common pathways, resembling the signaling routes of trophoblast invasion." (PMID 35625802, 2022). "STAT3, highly expressed in the multiple malignant tumors, is essential for growth and transformation of tumors." (PMID 36362294, 2022). "Mechanistically, IL-18-induced changes in the microbiota induce CC-chemokine ligand 5-driven inflammation, which accelerates epithelial cell proliferation through the regional activation of the IL-6/STAT3 pathway, eventually resulting in cancer formation." (PMID 36010693, 2022). "The IL-6/JAK/STAT3 regulatory axis interleukin-6 (IL-6) plays a central role in the pathogenesis of several cancers, including MM." (PMID 35326392, 2022). "Among the cancer-related proteins, signal transducer and activator of transcription 3 (STAT3) has been well documented to be inflammation and immunity." (PMID 36387401, 2022). "In conclusion, our data demonstrated that RT prevents against STAT3 excessive activation in skeletal muscle mediated by the overabundance of plasma IL-6 and muscle oxidative stress, a key role to attenuate cancer-induced muscle atrophy." (PMID 35847939, 2022). "Identifying specific and potent STAT3 inhibitors as a candidate substance in cancer therapy has attracted much attention." (PMID 34894961, 2022).
cancer (continued). "As an important mediator of inflammatory reaction and activator of STAT3, IL-6 can reduce the apoptosis of cancer cells." (PMID 35574420, 2022). "We will further determine the efficacy ofTTI-101, a small molecule inhibitor of both isoforms of STAT3 that is entering Phase II studies in cancer in CD in WT mice." (PMID 36498596, 2022). "It has been reported in the literature that ITGA2 plays a critical role in cancer cell progression and the regulation of PD-L1 by activating the STAT3 pathway." (PMID 35794161, 2022). "Conversely, STAT3 mainly maintains cancer cells survival and regulates immunosuppression and continuous inflammation in TME." (PMID 35330716, 2022). "Signal transducer and activator of transcription 3 (STAT3) is a widely-characterized oncogene in diverse human cancers." (PMID 35821160, 2022). "Sustained activation of signal transducer and activator of transcription 3 (STAT3) is a critical contributor in tumorigenesis and chemoresistance, thus making it an attractive cancer therapeutic target." (PMID 35843865, 2022). "Very recently, niclosamide has been shown to increase the efficacy of PD-1/PD-L1 immune checkpoint by the blockage of phosphorylated STAT3 to the promoter of PD-1, opening new possibilities for cancer immunotherapy through targeting STAT3." (PMID 35890135, 2022). "For the first time to our knowledge, we provide experimental evidence for the existence of a ROBO3/AXL/p-STAT3 regulatory axis in cancer." (PMID 35993361, 2022). "Baicalein showed potential anti-cancer activities through suppressing multiple malignant phenotypes as well as most possibly via inhibiting the activation of the STAT3 and Akt/NF-κB signaling pathways." (PMID 36432119, 2022). "Evidence suggests that abnormal STAT3 signaling promotes the occurrence and development of human cancers by inhibiting apoptosis, inducing cell proliferation, angiogenesis, invasion, and metastasis, as well as inducing inflammation and immunosuppression." (PMID 36092922, 2022). "Further, LIF from CAFs can act as a key paracrine(-reciprocal) factor for activating signal transducer and activator of transcription 3 (STAT3) signaling in cancer cells." (PMID 35159011, 2022). "In particular, we identified STAT3, which is a transcription factor with a central role in many types of cancer including GB, where it represents a convergence point of oncogenic pathways." (PMID 35562901, 2022). "The signal transducer and activator of transcription 3 (STAT3) is a pivotal transcriptional factor of multiple promoting genes in cancer development and immune evasion." (PMID 35563493, 2022). "PAK1 protein, a family of serine/threonine p21-activated kinases, is a regulator of cancer-inflammation signaling leading to the activation of STAT3 and NF-κB." (PMID 36012284, 2022). "STAT3 is indeed an oncogene that promotes cancer cell proliferation, motility, cell survival, and progression." (PMID 36144783, 2022). "IL-10 produced by cancer and stroma cells hinders the maturation of myeloid cells by activating STAT3." (PMID 35053426, 2022). "The transcription factors NF-kB and STAT3 play a crucial role in inflammation, tumorigenesis, immunosuppression and chemoresistance and are highly expressed in many cancers, including PM." (PMID 36232554, 2022). "IL-6 plays a crucial role in maintaining normal cell growth through STAT3 activation, and its aberrant activation results in the proliferation of cancer cells." (PMID 35956786, 2022). "Targeting the STAT3 signaling pathway has been a promising therapeutic strategy for numerous cancers, for it is the convergence of numerous oncogenic signaling pathways playing a vital role in regulating the antitumor immune response." (PMID 35698571, 2022). "In order to solve this problem, Shaomeng Wang’s research group used PROTAC technology to design a small molecule PROTAC 14 that can specifically degrade STAT3 in cancer cells." (PMID 36142231, 2022).
cancer (continued). "In PCa, JAK2/STAT3 can regulate the malignant phenotype of cancer cells through rewiring metabolic pathways." (PMID 35818076, 2022). "STAT3 is the key regulator of cell proliferation, survival and apoptosis and is constitutively activated in most human cancers." (PMID 35637970, 2022). "(-)-Antofine decreased STAT3 activation and reduced the translocation of STAT3, leading to the inhibition of cancer cell migration." (PMID 35805049, 2022). "JAK2/STAT3 signaling plays a crucial role in tumorigenesis—including cell proliferation and migration, radioresistance, and cancer cell stemness, and strategies targeting this pathway hold promise in anticancer drug development." (PMID 35269562, 2022). "Based on its important biological function in cancer, STAT3 has been investigated as a partial inhibitor for the next clinical therapeutic target in oncology." (PMID 36291659, 2022). "Signal transduction and transcription activator 3 (STAT3) is highly expressed in GC, and is closely related to cancer cell stage, invasion depth, lymph node metastasis, and cancer grade." (PMID 36120367, 2022). "In conclusion, this study confirmed that the IL-6/JAK/STAT3 signaling pathway is involved in the pathological process of “inflammation–atypical hyperplasia–cancer” in the AOM/DSS-induced UC animal model." (PMID 35946886, 2022). "In cancer cells, STAT3 transcribes many genes necessary for the growth and survival of cancer, such as VEGF." (PMID 35886918, 2022). "The excessive activation of STAT3 is closely related to the angiogenesis, invasion, and metastasis of various types of malignant tumors." (PMID 35252007, 2022). "The barriers against targeting the STAT3 pathway, the focus of future research on promising targets in the STAT3 pathway, and our perspective on the overall utility of STAT3 pathway inhibitors in cancer treatment are also discussed." (PMID 35356799, 2022). "STAT3 activation in cancer cells enhances the expression of IDO, which plays immunoregulatory roles in T-cells by regulating tryptophan metabolism." (PMID 36556226, 2022). "Activation of NF-κB and STAT3 signaling and transcriptional programs within cancer cells promote disease progression in multiple malignancies, including CRC56–60." (PMID 36253360, 2022). "The TLR-induced activation of key signaling pathways NF-κB and STAT3 promotes cancer pathogenesis in colon cancer, pancreatic cancer, hepatocellular carcinoma, and others." (PMID 36142391, 2022). "Targeting principal components of IL-6 signalling (e.g., IL-6Rs, gp130, STAT3, NF-κB) is an intensively studied approach in preclinical cancer research." (PMID 36429126, 2022). "The STAT3 signaling pathway is a major intrinsic pathway in cancer inflammation as it is frequently activated in malignant cells and can induce a large number of inflammations." (PMID 36686662, 2022). "Luteolin has anti-inflammatory effects via interactions with Janus kinase (JAK)/STAT3 and NF-κB pathways, and presents anti-cancer activities via modulating glucose metabolism, cell growth, and apoptosis." (PMID 36421353, 2022). "Circular RNA AKT3 (CircAKT3) is upregulated in cancer and inhibits miR-516b-5p, an inhibitor of STAT3, thereby promoting STAT3 activation and therapy resistance." (PMID 35646668, 2022). "The interaction between IL-8 from adipocytes and C-X-C chemokine receptor type-1 (CXCR1) on cancer cells activates the p38MAPK/STAT3 phosphorylation pathway initiating metastasis." (PMID 35269636, 2022). "This review summarizes the mechanisms of the STAT3 pathway regulation and the relationship between the STAT3 pathway and cancer hallmarks." (PMID 35356799, 2022). "IL-6 has been reported to contribute to inflammation and fibrosis, and to regulate the immune system and activate cancer-related signal transduction pathways, such as NF-κB and STAT3." (PMID 35277009, 2022). "STAT3 is a crucial transcription factor, which plays a role in development, inflammation, immunity, metabolism and cancer." (PMID 36119052, 2022).